NPL (N-acetylneuraminate pyruvate lyase)
Description:
Catalyzes the cleavage of N-acetylneuraminic acid (sialic acid) to form pyruvate and N-acetylmannosamine via a Schiff base intermediate. It prevents sialic acids from being recycled and returning to the cell surface. Involved in the N-glycolylneuraminic acid (Neu5Gc) degradation pathway. Although human is not able to catalyze formation of Neu5Gc due to the inactive CMAHP enzyme, Neu5Gc is present in food and must be degraded (Probable).
Synonyms: C1orf13; NPL1; DHDPS1; C112; NAL
Tractability: Antibody: the Human Protein Atlas places it where antibodies can reach. PROTAC: ubiquitination databases record sites on it; its protein half-life has been measured.
Gene: Protein-coding gene on chromosome 1 (182,789,293 to 182,831,017, forward strand). Ensembl gene ENSG00000135838.
Subcellular location: Cytoplasm
Subcellular location (Human Protein Atlas): Vesicles; Plasma membrane
Pathways (Reactome):
Metabolism of proteins: Sialic acid metabolism
Gene Ontology:
Molecular function: identical protein binding; N-acetylneuraminate lyase activity; protein binding; lyase activity
Biological process: N-acetylneuraminate catabolic process; carbohydrate metabolic process
Cellular component: cytosol; cytoplasm
Genetic constraint (gnomAD): Loss-of-function variants: 27 observed, 31.5 expected, observed/expected ratio (o/e) 0.86, 90% interval 0.63 to 1.18. The upper end of that interval is the gene's LOEUF score, 1.18, which puts it in group 5 of 6, group 1 being the genes least tolerant of losing a copy. Missense variants: 273 observed, 340.01 expected, observed/expected ratio (o/e) 0.8, 90% interval 0.73 to 0.89. Synonymous variants: 114 observed, 122.26 expected, observed/expected ratio (o/e) 0.93, 90% interval 0.8 to 1.09.
Homologues: Orthologues: chimpanzee NPL (99% identical), dog NPL (93% identical), pig NPL (92% identical), guinea pig NPL (89% identical), rat Npl (88% identical), mouse Npl (86% identical), macaque NPL (80% identical), tropical clawed frog npl (52% identical), zebrafish npl (52% identical). Paralogues in human: HOGA1 (25% identical).
Diseases named in the same sentence as NPL in open-access papers:
NPL is named in the same sentence as 16 diseases in open-access papers, as found by Europe PMC text mining. Sharing a sentence is not in itself a finding about the gene and the disease. The quoted sentences say what the papers report.
endometrial cancer (2 papers, 2020 to 2024). Primary or metastatic malignant neoplasm involving the endometrium (mucous membrane that lines the endometrial cavity). "A novel finding from this study is the association between deletions involving NPL and endometrial cancer risk (OR: 1.8, p = 0.001)." (PMID 39495297, 2024). "In particular, RASAL1 overexpression resulted significantly correlated with a worse outcome (increased death) in endometrial cancer, whereas NPL overexpression was correlated to a worse outcome in liver and renal cancers." (PMID 32906649, 2020).
cervical cancer (1 paper, 2025). A primary or metastatic malignant neoplasm involving the cervix. "GALNT12 and GCNT3 had HRs greater than 1, indicating that they were risk factors for cervical cancer, whereas GCNT4 and NPL had the reverse effect." (PMID 40352586, 2025). "In this research, GALNT12, GCNT4 and NPL were discovered as sialylation-related prognostic genes in cervical cancer, providing novel pathways for detection and treatment." (PMID 40352586, 2025). "This study utilized bioinformatics analysis based on public databases to identify key prognostic genes associated with cervical cancer, including GALNT12, GCNT4, and NPL." (PMID 40352586, 2025). "The outcomes of qRT-PCR revealed that GCNT4 and NPL were substantially increased in cervical cancer group, which corresponded to the expression trend in GSE63514 dataset." (PMID 40352586, 2025). "The findings from qRT-PCR demonstrated that GCNT4 and NPL were considerably overexpressed in the cervical cancer group." (PMID 40352586, 2025). "This study identified three key prognostic sialylation-related genes, GALNT12, GCNT4 and NPL, which showed significant differences in expression between cervical cancer samples and normal samples." (PMID 40352586, 2025). "Future studies could further explore the specific mechanisms of NPL and NANP in cervical cancer and their potential as therapeutic targets." (PMID 40352586, 2025).
renal carcinoma (1 paper, 2020). A carcinoma arising from the epithelium of the renal parenchyma or the renal pelvis. "As reported in Human Protein Atlas, NPL overexpression seemed to correlate with poor survival in liver and renal cancers, but little is known regarding the corresponding altered molecular pathways." (PMID 32906649, 2020).
infection (8 papers, 2015 to 2025). The state of being infected such as from the introduction of a foreign agent such as serum, vaccine, antigenic substance or organism. "In addition, G9P infection was associated with downregulation of another catalytic enzyme—NPL." (PMID 37848925, 2023). "Expression driven from the NPL and ENOD11 promoters gradually decreased in cells neighboring and underlying the infection site but remained high along the trajectory of infected cortical cells." (PMID 40613418, 2025). "Transcription factors classified as BBX-DBB, BBX-CO, DOF, MYB, REVEILLE, bZIP, NPL, ERF, AP2, NAC, and bHLH were revealed as differentially expressed in the susceptible cultivar during the BBTV infection process." (PMID 37907581, 2023). "The marker gene list for this subcluster included well-known infection-related genes like NPL, NF-YA1 and NIN and, as exemplified by NPL, were specific for this subpopulation." (PMID 37935666, 2023). "Consequently, and to avoid potential developmental side effects by constitutively and ectopically overexpressing NF-YA1, we first checked the cellular activation profile of two symbiosis-specific genes recruited during infection thread formation and growth, ENOD11 and NPL." (PMID 40613418, 2025). "We found no pronounced differences in nodulation gene expression between these clusters, which all comprised cells expressing NF-YA1 and NPL, suggesting that this pattern could be due to differences in cortical cell types rather than infection status." (PMID 37935666, 2023).
tumor (3 papers, 2020 to 2025). "However, as NPL expression declines, its anti-tumor function weakens, potentially facilitating tumor progression." (PMID 40352586, 2025). "In the early stages of macrophage differentiation, high NPL expression may promote differentiation into an anti-tumor phenotype, thereby inhibiting tumor progression." (PMID 40352586, 2025). "In this study, the expression of the NPL gene showed a trend of first increasing and then decreasing during macrophage differentiation, while the GALNT12 gene was expressed in tumor samples during the third stage of macrophage differentiation." (PMID 40352586, 2025). "Based on TCGA analysis for the downregulated genes from our RNA-Seq data, high gene signature comprising of TREM2, CATSPER1, NPL, and PRAM1 in tumor-infiltrating PMN-MDSC predicted poor OS rates in COAD patients." (PMID 33312958, 2020). "In tumor-infiltrating I-MDSC, high gene signature comprising of TNNT1, NPL and CATSPER1 predicted poor OS rates in COAD patients." (PMID 33312958, 2020). "The high expression of the NPL gene, by cleaving sialic acid and regulating the function of NOD-like receptors, also regulates the expression of T follicular helper cells, thereby promoting anti-tumor immune responses." (PMID 40352586, 2025). "Integrating NEU4 and NPL into the TSC1–mTORC1–sialylation axis further refines the mechanistic framework of PD-L1 hypersialylation–driven immune escape, highlighting a coordinated metabolic control of sialic acid turnover in tumor immune regulation." (PMID 41445741, 2025). "Furthermore, the interaction between NPL and NANP may play a crucial role in the sialylation modification of tumor cells, affecting tumor cell invasion, metastasis, and immune evasion." (PMID 40352586, 2025).
cancer (2 papers, 2020 to 2025). A tumor composed of atypical neoplastic, often pleomorphic cells that invade other tissues. "Instead, the contribution of NPL and POLN to BC predisposition was not supported by the additional screening of cancer cases." (PMID 32906649, 2020).
NPL also shares sentences with these, for which no sentence is quoted: Alzheimer disease (1 paper); atherosclerosis (1); Barrett esophagus (1); cardiovascular disorder (1); dementia (1); depression (1); endometriosis (1); gynaecological diseases (1); ischemic stroke (1); schizophrenia (1).